RSAD2 (radical S-adenosyl methionine domain containing 2)
Description:
Interferon-inducible antiviral protein which plays a major role in the cell antiviral state induced by type I and type II interferon. Catalyzes the conversion of cytidine triphosphate (CTP) to 3'-deoxy-3',4'-didehydro-CTP (ddhCTP) via a SAM-dependent radical mechanism. In turn, ddhCTP acts as a chain terminator for the RNA-dependent RNA polymerases from multiple viruses and directly inhibits viral replication. Therefore, inhibits a wide range of DNA and RNA viruses, including human cytomegalovirus (HCMV), hepatitis C virus (HCV), west Nile virus (WNV), dengue virus, sindbis virus, influenza A virus, sendai virus, vesicular stomatitis virus (VSV), zika virus, and human immunodeficiency virus (HIV-1). Also promotes TLR7 and TLR9-dependent production of IFN-beta production in plasmacytoid dendritic cells (pDCs) by facilitating 'Lys-63'-linked ubiquitination of IRAK1 by TRAF6. Plays a role in CD4+ T-cells activation and differentiation. Facilitates T-cell receptor (TCR)- mediated GATA3 activation and optimal T-helper 2 (Th2) cytokine production by modulating NFKB1 and JUNB activities. Can inhibit secretion of soluble proteins.
Synonyms: SAND; Viperin; CIG5; vig1; cig33
Tractability: Antibody: UniProt places it where antibodies can reach, with medium confidence. PROTAC: UniProt records ubiquitination sites on it; ubiquitination databases record sites on it.
Gene: Protein-coding gene on chromosome 2 (6,865,557 to 6,898,239, forward strand). Ensembl gene ENSG00000134321.
Subcellular location: Endoplasmic reticulum membrane; Golgi apparatus; Endoplasmic reticulum; Lipid droplet; Mitochondrion; Mitochondrion inner membrane; Mitochondrion outer membrane
Subcellular location (Human Protein Atlas): Endoplasmic reticulum; Nucleoli fibrillar center
Pathways (Reactome):
Immune System: Interferon alpha/beta signaling
Gene Ontology:
Molecular function: 4 iron, 4 sulfur cluster binding; protein binding; catalytic activity; iron-sulfur cluster binding
Biological process: defense response to virus; negative regulation of protein secretion; negative regulation of viral genome replication; response to virus; CD4-positive, alpha-beta T cell activation; CD4-positive, alpha-beta T cell differentiation; positive regulation of immune response; positive regulation of T-helper 2 cell cytokine production; positive regulation of toll-like receptor 7 signaling pathway; positive regulation of toll-like receptor 9 signaling pathway
Cellular component: endoplasmic reticulum; endoplasmic reticulum membrane; Golgi apparatus; lipid droplet; mitochondrial inner membrane; mitochondrial outer membrane; mitochondrion
Genetic constraint (gnomAD): Loss-of-function variants: 35 observed, 35.68 expected, observed/expected ratio (o/e) 0.98, 90% interval 0.75 to 1.3. The upper end of that interval is the gene's LOEUF score, 1.3, which puts it in group 5 of 6, group 1 being the genes least tolerant of losing a copy. Missense variants: 422 observed, 446.51 expected, observed/expected ratio (o/e) 0.95, 90% interval 0.87 to 1.02. Synonymous variants: 161 observed, 161.89 expected, observed/expected ratio (o/e) 0.99, 90% interval 0.87 to 1.13.
Homologues: Orthologues: chimpanzee RSAD2 (99% identical), macaque RSAD2 (96% identical), dog RSAD2 (84% identical), pig RSAD2 (83% identical), rabbit RSAD2 (83% identical), mouse Rsad2 (82% identical), rat Rsad2 (81% identical), guinea pig RSAD2 (80% identical), zebrafish rsad2 (69% identical), tropical clawed frog rsad2 (67% identical).
Diseases named in the same sentence as RSAD2 in open-access papers:
RSAD2 is named in the same sentence as 100 diseases in open-access papers, as found by Europe PMC text mining. Sharing a sentence is not in itself a finding about the gene and the disease. The quoted sentences say what the papers report.
viral infection (74 papers, 2010 to 2025). "RSAD2 (Radical s-adenosyl methionine domain containing 2) encoded a vital enzyme for innate immune responses as it was expressed in multiple kinds of cells in response to inflammatory stimuli (including viral infection)." (PMID 35795789, 2022). "RSAD2 is an interferon-regulated gene associated with innate immune response during viral infections." (PMID 30630417, 2019). "RSAD2, also known as Radical S-adenosyl methionine domain-containing 2, is an interferon-stimulated gene that is significantly upregulated upon viral infection." (PMID 40300035, 2025). "RSAD2 participates in differentiation of macrophages and T cells and can protect animals from viral infections." (PMID 41472112, 2025). "Many studies have explored RSAD2 localization as it has been found in a variety of cellular compartments, all of which are dependent on the viral infection present." (PMID 40024473, 2025). "Viperin (RSAD2) is a prototypical interferon-stimulated gene, and its overexpression resembles a “viral infection-like” state." (PMID 41267080, 2025). "RSAD2 is upregulated by viral infection or IFN-I/II signalling through the Janus kinase signal transducer and activator of transcription (JAK-STAT) pathway." (PMID 39334325, 2024). "Dendritic cells secrete genes like Radical S-Adenosyl Methionine Domain Containing 2 (Rsad2) to prevent viral infection (downregulated at D21 and D28)." (PMID 36834981, 2023). "The adaptive behavior of NK cells during viral infection is facilitated through STAT1-mediated epigenetic control of RSAD2." (PMID 38162574, 2023). "The classical signaling pathway for RSAD2 induction in response to viral infection is dependent on type I IFN signaling transduction." (PMID 36180831, 2022). "Although AMPKα plays a critical role in the regulation of energy homeostasis, it has been found to promote antiviral immunity in response to viral infection, and AMPKα activation restricts viral replication via upregulation of the antiviral effector RSAD2." (PMID 36180831, 2022). "The expression of RSAD2 increased with the prolongation of virus infection time, and reached the maximum at 36–48 hpi." (PMID 36423196, 2022). "RSAD2 is an interferon-stimulated gene involved in innate immunity and subsequent adaptive immunity during viral infection, as such is mainly responsible for limiting viral replication and antiviral responses." (PMID 32897243, 2020). "IFN-α/β stimulates the activation of hundreds of IFN-stimulated genes (ISGs, e.g., CXCL10, RSAD2, etc.), the first line of defence against viral infection." (PMID 32599823, 2020). "IFIT proteins and RSAD2 are among interferon –stimulating genes that are induced by viral infection to suppress the virus infectivity." (PMID 30619083, 2018). "This enrichment may be attributed to the increased expression of ISGs like MX1 and RSAD2 during the early stages of the viral infection, leading to a higher demand for enzymes and energy production in organelles such as mitochondria." (PMID 38673764, 2024). "Under-expression of MX1, ISG15, RSAD2, IFIT1, and OAS2 may weaken the ability of the immune system to effectively counter viral infections, leaving the heart tissues susceptible to viral invasion and potentially contributing to MMVD progression." (PMID 38753730, 2024). "Notably, RSAD2 was significantly upregulated in mRNA and protein levels after viral infection, suggesting that RSAD2 was involved in antiviral response in T. sinensis." (PMID 38067016, 2023). "In macrophages, the cellular activity of RSAD2 may provide a protective mechanism for cells against viral infection or other conditions that increase ROS levels." (PMID 35155543, 2022). "The role of RSAD2 and progression to type 1 diabetes may be through its role in mounting an inflammatory response to viral infection of beta-cells." (PMID 33154504, 2020).
viral infection (continued). "The majority of the top 50 predictive genes contained in each factor are known to characterize host response to viral infection, and include RSAD2, the OAS family, multiple interferon response elements, the myxovirus-resistance gene MX1, cytokine response pathways and others." (PMID 23326326, 2013). "Therefore, RSAD2 might control the cell response to inflammatory stimuli, including viral infection, by regulating cell metabolism." (PMID 35795789, 2022). "Thus, viral infection in the disease challenge may activate RSAD2 expression, which decreases growth rate and increases treatment and mortality rates." (PMID 35100362, 2022). "Moreover, the other antiviral response markers selected for this study in red tilapia, including irf-3, Mx, and VIPERIN (or rsad-2), were previously found to be strongly induced during several viral infections in other teleosts and involved in the IFN response in tilapia." (PMID 33172079, 2020). "Upregulation of the Stat1-mediated response to the virus, interferon response, immune system activation, and interferon-stimulated genes (ISGs; e.g., Rsad2, IFITM3, Cxcl9, Bst2, and Oas2) across all strains confirmed ongoing viral infection." (PMID 39875898, 2025). "Upregulation of the Stat1-mediated response to the virus, interferon response, immune system activation, and ISGs, such as Rsad2, IFITM3, Cxcl9, Bst2, and Oas2, across all strains confirmed ongoing viral infection." (PMID 39875898, 2025). "RSAD2 is a direct modulator of GAPDH activity and is typically activated by interferon in immune cells during viral infection." (PMID 39334961, 2024). "VirSig was defined as the signature of the host response to viral infection using the average expression of five representative genes, including IFI27, RSAD2, IFI44L, ISG15 and IFITM3." (PMID 38790931, 2024). "IFIT5 is a factor in HCV entry, HCLS1 is a newly identified transcription regulator, and RSAD2 and IFIT5 are ISGs that have been shown to be critically important to resistance to viral infection, including influenza virus, HIV-1, and other viruses." (PMID 37896995, 2023). "In our data, the enriched pathways were related to viral infections such as influenza A (MX1, OAS1, OAS2, OAS3, RSAD2, STAT1) and measles (MX1, OAS1, OAS2, OAS3, STAT1)." (PMID 35464437, 2022). "ISG15, IRF7, MX1, RSAD2, and IFIT3 have been found to play a vital role in modulating immune response against the viral infection." (PMID 34631844, 2021). "We cloned chicken MX1, IFI6, IFIT5, RSAD2, and OASL into eukaryotic expression vector and evaluated their effects on virus infection in DF1 cells." (PMID 32183248, 2020). "RSAD2 and IDO1 are mainly triggered by interferons as part of the concerted counteraction against viral infection." (PMID 32849329, 2020). "IRF1 further regulates RSAD2 (> 2258.2-fold change, FDR p-value 5.2 × 10− 25), which has been reported to be highly expressed during viral infections." (PMID 30621583, 2019). "However, it is noteworthy that RSAD2 could protect against SINV and WNV, which cause acute inflammation in the CNS, suggesting that in CNS, a relatively sterile environment, RSAD2 may exert critical role in combating viral infection." (PMID 26008703, 2015). "In particular, interferon stimulated pathways such as those including RSAD2, IRF7, MX1, OAS3, MDA-5, RIG-I and others are incorporated and thought to drive both innate and, to a lesser degree, adaptive immune responses to viral infection." (PMID 23326326, 2013). "In noncancerous cells, during viral infection, RSAD2 is upregulated and induced mainly by interferon signaling pathways which enhance the activity of T-cells and alter metabolic processes that attack the virus." (PMID 40024473, 2025). "Together, this indicates that primary microglia are already in an antiviral state with high expression of Rsad2, independent of virus infection." (PMID 39205301, 2024).
viral infection (continued). "Apart from this similarity, different virus infection pathways owned their unique genes, with STAT1,RSAD2 and IRF9 in the influenza A pathway,IL-2RA,IL-2RB and CD40 in the HTLV-1 infection pathway, HCFC1, MAP3K7, SOCS3, IRF9, HMGN1, and FAS in the herpes simplex infection pathway." (PMID 35795668, 2022). "Furthermore, 14 proteins that were upregulated after virus infection—including TNFaIP3, HNRNPH2, RSAD2, ISG20, IDO1, and KCNN4—also exhibited significantly increased mRNA levels relative to uninfected cells (p < 0.05)." (PMID 36423196, 2022). "We also show that IL22 reduces the expression of viral entry receptors (e.g. ACE2, TMPRSS2, DPP4, CD46 and TNFRSF14), increases the expression of anti-viral proteins (e.g. RSAD2, AOS, ISG20 and Mx1) and, consequently, reduces the viral infection of neighboring cells." (PMID 34045640, 2021). "In the upregulated genes in both chMDA5 and poly(I:C) groups, many genes were ISGs, such as MX1, IFI6, IFIT5, RSAD2, OASL, and, CMPK2, which suggested that these genes might play important roles in restricting virus infection in chicken." (PMID 32183248, 2020). "Host cells sense viral infections through various pattern recognition receptors (PRRs) and initiate innate immune responses, especially activation of the IFN response to produce a variety of antiviral proteins such as RSAD2 and Mx1 to fight against viral infections." (PMID 38257818, 2024). "In contrast, IRF7 and RSAD2 were not induced by viral infection of ΔIRF7 cells." (PMID 34411201, 2021). "RSAD2, as an antiviral protein, could restrict the amplification of DNA or RNA viruses by blocking the positive-sense RNA amplification during the early stages of the virus infection, targeting viral nonstructural proteins to promote its proteasomes degradation, or disrupting the lipid rafts." (PMID 36680075, 2022). "Notably, we discovered upregulation of multiple ISGs, such as ZBTB16, MX1, OASL, RSAD2, CMPK2, and CXCL14 in the DiMNF treated primary cells, even in the absence of viral infection." (PMID 37672505, 2023).
COVID-19 (28 papers, 2020 to 2025). A disease caused by infection with severe acute respiratory syndrome coronavirus 2. "This indicates that the upregulation of RSAD2 is associated with better clinical outcomes in COVID-19 patients." (PMID 39637135, 2024). "The DEGs analysis of the overlapping genes in postmortem lung tissue from COVID-19 cases and acute lung injury (ALI) murine model found that RSAD2 had a high degree centrality in a COVID-19-associated regulatory network." (PMID 35625619, 2022). "A significant increase in RSAD2 was previously identified in COVID-19 patients compared to healthy controls." (PMID 39637135, 2024). "We found that upregulated expression of MX1, and RSAD2 was a prognostic factor of COVID-19 treatment." (PMID 39172244, 2024). "Work of Giovannoni and coauthors revealed increased expression levels of RSAD2 in COVID-19 and found substantial correlation of RSAD2 with viral load." (PMID 37053191, 2023). "Moreover, a lower respiratory tract transcriptomic study revealed that RSAD2 expression correlated with the viral load in mild and severe COVID-19." (PMID 35625619, 2022). "However, PML and RSAD2 expression levels were significantly upregulated in COVID-19 patients bearing high and medium viral load." (PMID 34446714, 2021). "Previous research has highlighted the up-regulation of genes such as IFI44L, IFFI44, RSAD2, OAS1, EPSTI1, and OSAL in COVID-19, contributing to immune regulation." (PMID 38601162, 2024). "In this study, the highest differentially expressed genes in COVID-19 (+) tissue, including ISG15 itself, IFIT1, RSAD2, OAS1, MX1, OASL, and IFIT3, are all important for the ISG15 pathway’s progression and are part of the lung tissue’s antiviral response." (PMID 38932146, 2024). "Studies have found that IFFI44, IFI6, RSAD2, and OSAL are significantly up-regulated in COVID-19 patients and are involved in immune regulation." (PMID 36911695, 2023). "The AUC of genes in the COVID-19 cohort are as follows: IFI6, 0.678; IFI27, 0.866; IFI44L, 0.786; OASL, 0.834; RSAD2, 0.770." (PMID 36911695, 2023). "Seven common DEGs (PPARGC1A, FUBP1, ITGB8, SYCP2, RSAD2, FGF1, and FERMT1) were identified from the GSE164805 dataset of patients with mild COVID-19, and the GSE50395 dataset from APS patients." (PMID 36241659, 2022). "Global neutrophil expression aligned with neutrophil state-specific markers, such as interferon response genes (IFITM1, RSAD2, IFI6 and ISG10), being more highly expressed in COVID-19 neutrophils." (PMID 34782790, 2022). "A significant decrease was observed for FI44L, MX1, RSAD2, ISIG15, and IFIT1 indicating a dysregulated type I/III interferon response in COVID-19 patients with pneumonia with a downregulation of ISGs." (PMID 34197543, 2021). "In addition, RSAD2 and IFITM3 were among the consensus up-regulated genes in our previous meta-analysis of COVID-19 transcriptome datasets." (PMID 40872774, 2025). "An additional 8 targets (CXCL6, IFI44, IFI44L, RSAD2, S100A8, SPRR2A, SYNE1, XAF1) are associated with COVID-19 pathogenesis, but do not have therapies targeting them available for potential repurposing." (PMID 34582497, 2021). "Furthermore, this CA dimension correlated with a subset of blood neutrophils that specifically expressed ISGs such as IFIT1, RSAD2, and OAS3 but also PD-L1, suggesting that a high-viral load in the lung can significantly influence the blood immune landscape in COVID-19 patients." (PMID 33674591, 2021). "RSAD2 and IL1R2 were also found to be involved in regulation of SARS-CoV-2 infection, however their expression were positively correlated only with viral load and viral shedding time, whereas their association with COVID-19 severity has not yet been shown." (PMID 34807957, 2021). "OASL, RSAD2, ISG20, IFI16, and IFIT1 were not previously annotated in the COVID-19 KEGG pathway." (PMID 38580667, 2024).
influenza (9 papers, 2013 to 2024). An acute viral infection of the respiratory tract, occurring in isolated cases, in epidemics, or in pandemics; it is caused by serologically different strains of viruses (influenzaviruses) designated A, B, and C, has a 3-day incubation period, and usually lasts for 3 to 10 days. "Viperin (RSAD2) is an antiviral protein that can inhibit influenza budding from the plasma membrane by interfering with lipid rafts." (PMID 26810609, 2016). "The influenza group’s validation experiment showed significant differences in all six genes (IFI44L, IFI44, RSAD2, IFIT3, EIF2AK2, and IFI27)." (PMID 38601162, 2024). "They found that interferon-related genes such as RSAD2, LAMP3, IFI44L, and OAS1 were significantly differentially expressed in individuals with symptomatic RSV, influenza, or HRV infection." (PMID 24265599, 2013). "Rsad2, Cxcl10, Saa3, Irf7, and Il1rn, which have been reported in influenza, whereas the role of LCN2 in influenza was still unknown." (PMID 35495713, 2022).
autoimmune disease (7 papers, 2014 to 2025). A disorder resulting from loss of function or tissue destruction of an organ or multiple organs, arising from humoral or cellular immune responses of the individual to their own tissue constituents. "Some research has detected the association between RSAD2 and multiple autoimmune diseases, such as RA, SLE, and AS." (PMID 37465678, 2023). "RSAD2 activates the immune response and has been associated with multiple autoimmune diseases, such as RA, SLE, and AS." (PMID 34180358, 2021).